SCARA5 (scavenger receptor class A member 5)
Description:
Ferritin receptor that mediates non-transferrin-dependent delivery of iron. Mediates cellular uptake of ferritin-bound iron by stimulating ferritin endocytosis from the cell surface with consequent iron delivery within the cell. Delivery of iron to cells by ferritin is required for the development of specific cell types, suggesting the existence of cell type-specific mechanisms of iron traffic in organogenesis, which alternatively utilize transferrin or non-transferrin iron delivery pathways. Ferritin mediates iron uptake in capsule cells of the developing kidney. Preferentially binds ferritin light chain (FTL) compared to heavy chain (FTH1).
Synonyms: FLJ23907; MGC45780; NET33; Tesr
Tractability: Antibody: UniProt places it where antibodies can reach, with medium confidence; UniProt predicts a signal peptide or a membrane-spanning region; its Gene Ontology location is reachable by antibodies, with medium confidence.
Gene: Protein-coding gene on chromosome 8 (27,869,883 to 27,992,834, reverse strand). Ensembl gene ENSG00000168079.
Subcellular location: Cell membrane
Pathways (Reactome):
Vesicle-mediated transport: Scavenging by Class A Receptors
Gene Ontology:
Molecular function: ferritin receptor activity; scavenger receptor activity
Biological process: endocytosis; intracellular iron ion homeostasis; iron ion transmembrane transport; protein homotrimerization
Cellular component: plasma membrane; cell surface; membrane
Genetic constraint (gnomAD): Loss-of-function variants: 39 observed, 36.55 expected, observed/expected ratio (o/e) 1.07, 90% interval 0.82 to 1.39. The synonymous counts are far from expectation, so gnomAD's model fits this gene poorly and the ratio says little. Missense variants: 676 observed, 631.25 expected, observed/expected ratio (o/e) 1.07, 90% interval 1 to 1.14. Synonymous variants: 332 observed, 274.57 expected, observed/expected ratio (o/e) 1.21, 90% interval 1.11 to 1.32.
Homologues: Orthologues: chimpanzee SCARA5 (96% identical), macaque SCARA5 (93% identical), dog SCARA5 (93% identical), rabbit SCARA5 (92% identical), mouse Scara5 (87% identical), rat Scara5 (86% identical), tropical clawed frog scara5 (61% identical), guinea pig SCARA5 (56% identical), zebrafish scara5 (49% identical). Paralogues in human: MSR1 (32% identical), MARCO (23% identical), COLEC12 (22% identical).
Diseases named in the same sentence as SCARA5 in open-access papers:
SCARA5 is named in the same sentence as 67 diseases in open-access papers, as found by Europe PMC text mining. Sharing a sentence is not in itself a finding about the gene and the disease. The quoted sentences say what the papers report.
breast carcinoma (13 papers, 2012 to 2025). "Moreover, the Scara5 gene, which is associated with tumor suppression in liver, lung, and breast cancer, and osteosarcoma, showed upregulation in the H&N▶Diff-H group." (PMID 35326510, 2022). "SCARA5 is downregulated in breast cancer and acts as a tumor suppressor by regulating metabolism and immune responses." (PMID 40565055, 2025). "A strong convergence was also observed for breast cancer: all manuscript-listed genes, including SCARA5, ADAMTS5, MMP11 and CAVIN2, appeared in the outputs of SHAP or LIME." (PMID 40565055, 2025). "Another subunit of ferritin, the L-chain, has been found to specifically interact with scavenger receptor class A member 5 (SCARA5) which is upregulated in breast cancer stem cells." (PMID 36678860, 2023). "SCARA5 significantly inhibited cell proliferation, invasion, and migration, and induced G0/G1 arrest and apoptosis of breast cancer cells." (PMID 33758617, 2021). "SCARA5 plays an important role in tumourigenesis and metastasis of breast carcinoma by inhibiting ERK1/2, STAT3 and AKT pathways." (PMID 33247676, 2020). "Up-regulated expression of COL10A1, MMP11, CST1, GJB2, MMP1, MMP13, and CEACAM6; down-regulated expression of ADH1B, CIDEC, THRSP, GPD1, TIMP4, FABP4, and SCARA5 genes was common in breast cancers of the two populations." (PMID 31292488, 2019). "In breast cancer, SCARA5 blocks ERK1/2, Akt, and STAT3 pathway activities." (PMID 38891888, 2024). "Hspb7, Mb, Cox7a1, Fbp2, and Scara5 have all previously been identified as tumor suppressor genes in breast cancer, non-small cell lung cancer, gastric cancer, sarcoma, and hepatocellular carcinoma, wherein they can suppress tumor cell invasion, proliferation, and migration." (PMID 34194323, 2021). "A recent study showed that ferritin could deliver curcumin into human breast cancer cell MCF-7 over-expressed ferritin receptors Scara5 and TFR1." (PMID 29789480, 2018). "In this study, we show that CSC-enriched tumorspheres from breast cancer cell lines display an increased L-Ferritin uptake capability compared to their monolayer counterparts as a consequence of the upregulation of the L-Ferritin receptor SCARA5." (PMID 27579532, 2016). "Recently, the ferritin receptor, Scara5, has been included in a prognostic gene panel for breast cancer indicating that the capability of cancer cells to uptake ferritin may confer a survival or proliferative advantage." (PMID 23300545, 2012). "Overexpression of SCARA5 downregulated MMP-2, MMP-3 and MMP-9 in breast cancer cell." (PMID 33758617, 2021). "Furthermore, SCARA5 inhibits breast cancer cell proliferation, colony formation, invasion, and migration by inhibiting the phosphorylation of AKT, STAT3, and ERK1/2 and also induces breast cancer cell apoptosis." (PMID 37035142, 2023).
hepatocellular carcinoma (12 papers, 2014 to 2025). A malignant tumor that arises from hepatocytes. "SCARA5 expression is also usually downregulated in hepatocellular carcinoma due to high promoter methylation and allele imbalance." (PMID 34631779, 2021). "Over-expression of SCARA5 suppressed some malignant behaviors in hepatoma cells, and SCARA5 knockdown was associated with activation of MMP9." (PMID 24950699, 2014). "Studies have shown that SCARA5 deficiency suppresses ferroptosis in tumour cells, thereby impairing immune activation within the TME and increasing the resistance of hepatocellular carcinoma (HCC) cells to sorafenib." (PMID 40299520, 2025). "So far, SCARA5 has been previously proved as a candidate tumor suppressor for hepatocellular carcinoma (HCC), BC, and other tumors." (PMID 35755171, 2022). "SCARA5 has been reported to function as a tumor suppressor gene in several types of cancer previously, such as human hepatocellular carcinoma (HCC) 5, colorectal cancer 6, glioma 7, lung cancer 7,8 and breast cancer." (PMID 33758617, 2021). "Numerous studies have suggested that SCARA5, a member of the scavenger receptor family, is involved in the molecular mechanisms of various cancers such as hepatocellular carcinoma." (PMID 32448271, 2020). "SCARA5, which was proposed as a tumor suppressor gene in hepatocellular carcinoma, was down-regulated in various tumor samples, and may play a role in colorectal carcinogenesis." (PMID 24516561, 2014). "documented methylation in the SCARA5 promoter region of Hepatocellular carcinoma (HCC) cells, accounting for low SCARA5 expression and hence enhanced in vivo tumorigenicity, cell invasion, and tumor metastasis." (PMID 37035142, 2023).
lung carcinoma (5 papers, 2021 to 2025). "By use of the TCGA database, we found SCARA5 expression to be low in lung cancer and high in paracancerous tissues and this observation was related to hypermethylation of the SCARA5 promoter." (PMID 34150631, 2021). "We found SCARA5 to be downregulated in lung cancer cell lines and tissues with SCARA5 levels negatively related to promoter methylation." (PMID 34150631, 2021). "In this study, we found that re-expression of SCARA5 can inhibit cell proliferation, reduce lung cancer xenograft tumor growth, and arrest A549 cells in the G2/M phase of the cell cycle." (PMID 34150631, 2021). "Bioinformatics, methylation-specific polymerase chain reaction (MSP), quantitative real-time PCR, and immunohistochemistry were used to assess promoter methylation and expression of SCARA5 in lung cancer tissues and cell lines." (PMID 34150631, 2021). "First, we analyzed SCARA5 expression in 409 lung cancer tissues (including 50 paired normal lung tissues) using The Cancer Genome Atlas (TCGA) database." (PMID 34150631, 2021). "In this study, for the first time, we found that methylation of the SCARA5 promoter silenced lung cancer gene expression." (PMID 34150631, 2021). "Taken together, these data suggest that SCARA5 has an Inhibitory effect on lung cancer cells both in vitro and in vivo." (PMID 34150631, 2021). "In summary, SCARA5 was silenced in non-small cell lung cancer by promoter methylation, which related to prognosis, apoptosis, and cell cycle arrest in lung cancer cells." (PMID 34150631, 2021). "Collectively, these data suggest that SCARA5 is downregulated in lung cancer due to promoter methylation and that SCARA5 downregulation is positively related to prognosis." (PMID 34150631, 2021). "A previous report has shown that SCARA5 knockdown contributes to epithelial-to-mesenchymal transition-induced migration in lung carcinoma A549 cells." (PMID 34417976, 2021). "By detection of methylation and gene expression levels in lung cancer tissues, we found the promoter of SCARA5 to be hypermethylated and SCARA5 protein levels to be decreased, which is consistent with the database results." (PMID 34150631, 2021). "Taken together these data suggest that promoter methylation of the SCARA5 gene results in SCARA5 gene silencing in lung cancer." (PMID 34150631, 2021). "After demethylation, the expression of SCARA5 in lung cancer cells was upregulated, which indicates that SCARA5 hypermethylation results in low SCARA5 gene expression." (PMID 34150631, 2021). "The ectopic expression of SCARA5 inhibited the proliferation of lung cancer cells in vitro and the growth of xenograft tumors in vivo." (PMID 34150631, 2021). "Hypermethylation of the SCARA5 promoter in these types of lung cancer was significantly related to decreased expression of SCARA5." (PMID 34150631, 2021). "Ectopic expression of SCARA5 suppressed proliferation of lung cancer both in vitro and in vivo through upregulation of HSPA5 expression, which inhibited FOXM1 expression resulting in G2/M arrest of the A549 cell line." (PMID 34150631, 2021). "In order to understand the role of SCARA5 in lung cancer, we conducted a series of bioinformatics analyses." (PMID 34150631, 2021). "Compared to normal tissue, SCARA5 immuno-reactivity was significantly lower in lung cancer." (PMID 34150631, 2021). "The inhibitory effect of SCARA5 on lung cancer in vivo was assessed." (PMID 34150631, 2021). "Thus, we conclude that SCARA5 induces apoptosis and cell cycle arrest in lung cancer cells." (PMID 34150631, 2021). "Although few samples had mutations in PBK, we observed that mutations in CNV accounted for the majority of PBK gene DNA alterations in all lung cancer patients and found a high proportion of LUAD patients with CNV with multiple tumor suppressor genes, such as CCDC25, SCARA5 and EPHX2." (PMID 37993518, 2023).
non-small cell lung carcinoma (5 papers, 2018 to 2025). A group of at least three distinct histological types of lung cancer, including non-small cell squamous cell carcinoma, adenocarcinoma, and large cell carcinoma. "G9a and DNMT1 by CM272 severely reduce methylation of SCARA5 and AOX1promoter and increase the efficacy of non-small cell lung cancer (NSCLC)." (PMID 39996888, 2025). "SCARA5 is a scavenger receptor, and SCARA5 levels are significantly lower in glioma and non-small cell lung cancer tissues compared with normal tissue." (PMID 30249289, 2018). "Thus, for non-small cell lung cancer (NSCLC), SCARA5 acts as a tumor suppressor that may serve as a marker for cancer prognosis and for clinical guidance during chemotherapy." (PMID 34150631, 2021).
bladder cancer (4 papers, 2022 to 2025). "Exosomes derived from PTENP1-overexpressing BMMSCs abolished the promotion of miR-17 overexpression or SCARA5 knockdown on the malignant phenotype of bladder cancer cells." (PMID 38994350, 2024). "Exosomal long non-coding RNA (lncRNA) PTENP1, which is released by hBM-MSCs, inhibits the aggressive phenotypes of Bladder cancer cells (5637 and T24) by controlling the miR-17/SCARA5 axis." (PMID 36684446, 2022). "BMSC-derived exosomes can transport lncRNA PTENP1 into bladder cancer cells, and lncRNA PTENP1 inhibits the malignant phenotype of bladder cancer cells by regulating the miR-17/SCARA5 axis." (PMID 40647484, 2025). "In order to promote the expression of SCARA5, exosomal lncRNA PTENP1 sponges miR-17 to prevent bladder cancer cell malignant behaviors as the mechanism." (PMID 36684446, 2022).
gastric cancer (4 papers, 2021 to 2025). A primary or metastatic malignant neoplasm involving the stomach. "Of 19 cases of genetically altered gastric cancer, 13 cases had SCARA5 mutation, 5 cases had deep deletion and 1 case had amplification." (PMID 33758617, 2021). "Our data showed that upregulated expression of SCARA5 significantly suppressed proliferation, migration and invasion of gastric cancer cells in vitro." (PMID 33758617, 2021). "The potential functions of SCARA5 in gastric cancer cell growth, migration and invasion were further examined by overexpression plasmid transfection." (PMID 33758617, 2021). "Taken together, we proposed that SCARA5 acted as a tumor suppressive factor, and it had great potential to be a gene target in cancer treatment and a clinical biomarker in diagnosing gastric cancer." (PMID 33758617, 2021). "The mRNA and protein level of SCARA5 in gastric cancer tissues (n=36) and adjacent non-tumor tissues (n=16) was detected by qRT-PCR and western blot." (PMID 33758617, 2021). "Results demonstrated that the SCARA5 expression was significantly lower in gastric cancer tissues than in the adjacent non-tumor tissues." (PMID 33758617, 2021). "However, its biological roles and mechanism of SCARA5 in gastric cancer (GC) have not been elucidated." (PMID 33758617, 2021). "Thus, SCARA5 plays an important role in the suppression of EMT, and SCARA5 might inhibit gastric cancer cells aggressiveness by influencing EMT initiation." (PMID 33758617, 2021). "However, the expression, biological function and clinical significance of SCARA5 in the progression and metastasis of gastric cancer have not been fully understood." (PMID 33758617, 2021).
osteosarcoma (4 papers, 2020 to 2023). A usually aggressive malignant bone-forming mesenchymal neoplasm, predominantly affecting adolescents and young adults. "On the one hand, SCARA5 expression is downregulated relative to normal tissues in 18 tumors, including esophageal adenocarcinoma (EAC), osteosarcoma, BC, and CRC." (PMID 35755171, 2022).
atherosclerosis (3 papers, 2021 to 2022). A disease characterized by the build-up of fatty material and calcium deposition in the arterial wall resulting in partial or complete occlusion of the arterial lumen. "Fourth, a recent study on atherosclerosis found that the proliferating and migrating abilities of aortic smooth muscle cells were significantly inhibited after SCARA5 KD." (PMID 35755171, 2022). "Knockdown of SCARA5 inhibits human aortic smooth muscle cell proliferation and migration, a critical step in the progression of atherosclerosis." (PMID 35008858, 2021).
colorectal cancer (3 papers, 2021 to 2022). A primary or metastatic malignant neoplasm that affects the colon or rectum. "Most studies on SCARA5 are tumor related, involving BC, colorectal cancer (CRC), LC, and other cancers." (PMID 35755171, 2022). "Besides, comprehensive analysis showed that SCARA5 might be a suppressor gene in colorectal cancer." (PMID 34559577, 2021).
ischemic stroke (3 papers, 2021 to 2026). A stroke disorder caused by obstruction of blood flow to the brain, due to thrombotic (local blood clot formation) or embolic (due to a blood clot or other material traveling from another site) event. "Analyses of circulating proteome in ischemic stroke patients revealed 7 potential biomarkers for stroke risk and SCARA5 as a new drug target." (PMID 39015225, 2024). "In conclusion, we found causal evidence supporting three classic genes MMP12, F11 and SCARA5, and three novel genes SH3BGRL3, SWAP70 and SPATA20 were associated with the risk of ischemic stroke and their subtypes." (PMID 41488603, 2026). "Furthermore, recent studies have reported TWEAK, matrix metallopeptidase 12, CD40, and scavenger receptor class A member 5 as promising targets for the treatment of ischemic stroke." (PMID 33263724, 2021). "We also found that SCARA5 and SWAP70 were related to stroke and ischemic stroke at the transcriptome level." (PMID 41488603, 2026).
liver cancer (3 papers, 2020 to 2022). An epithelial or non-epithelial malignant neoplasm that arises from the liver. "Recent studies have reported SCARA5 methylation levels to be elevated and expression levels to be decreased in liver cancer and breast cancer." (PMID 34150631, 2021). "In breast and liver cancer, promoter hypermethylation of SCARA5 results in low gene expression, which promotes the process of tumor malignancy." (PMID 34150631, 2021). "SCARA5 expression is significantly downregulated in various tumor tissues including liver cancer (LC), rectal cancer, and glioblastoma and might affect cell proliferation and invasion abilities by the focal adhesion kinase (FAK) signaling pathway and epithelial-mesenchymal transition (EMT)." (PMID 35755171, 2022).
prostate carcinoma (3 papers, 2020 to 2023). A carcinoma that arises from epithelial cells of the prostate gland. "In the present study, we studied the function of a novel miRNA, miR-4287, another miRNA that falls on chromosome 8p 21.1 (GRCh38.p13) within intron of gene scavenger receptor class A member 5 (SCARA5), in prostate cancer cell lines." (PMID 33473254, 2020). "To our knowledge, we are the first to investigate the role of SCARA5 in prostate cancer and we demonstrated that SCARA5 might be a potential biomarker in prostate cancer." (PMID 37443605, 2023).
Stroke (3 papers, 2023 to 2026). Sudden impairment of blood flow to a part of the brain due to occlusion or rupture of an artery to the brain. "The PWAS identified 7 genes (MMP12, F11, ENGASE, SH3BGRL3, SPATA20, SWAP70, SCARA5) whose cis-regulated plasma protein levels were associated with stroke and its subtypes at a FDR of P < 0.05." (PMID 41488603, 2026). "In a study using Mendelian randomization to identify biomarkers for stroke, SCARA5 levels were associated with a decreased risk of SAH, potentially implicating SCARA5 in baseline risk for hemorrhage." (PMID 38283681, 2023). "We identified 7 potential risk genes (MMP12, F11, SH3BGRL3, ENGASE, SCARA5, SWAP70 and SPATA20) of stroke with altered protein abundances in the plasma." (PMID 41488603, 2026). "We found that the protein abundance of seven genes (MMP12, F11, SH3BGRL3, ENGASE, SCARA5, SWAP70 and SPATA20) in the plasma was associated with stroke and its subtypes, and six genes (MMP12, F11, SH3BGRL3, SCARA5, SWAP70 and SPATA20) causally related with stroke and its subtypes." (PMID 41488603, 2026).
thyroid cancer (3 papers, 2020 to 2021). "SCARA5 also modulated the expression of epithelial-mesenchymal transition-related proteins in thyroid cancer." (PMID 33758617, 2021).
esophageal squamous cell carcinoma (2 papers, 2022 to 2023). Esophageal squamous cell carcinoma (ESCC) is a type of esophageal carcinoma (EC) that can affect any part of the esophagus, but is usually located in the upper or middle third. "Recently, scavenger receptor class A member 5 (SCARA5) was reported to be the downstream gene of THSD7A in esophageal squamous cell carcinoma." (PMID 37443605, 2023).